CD4 (CD4 molecule)
Diseases named in the same sentence as CD4 in open-access papers (continued):
Sharing a sentence is not in itself a finding about the gene and the disease.
infection (continued). "The stability of latently-infected resting memory CD4+ T-cells is not, for the most part, due to new de novo infection events during HAART, but rather to the ability of resting memory CD4+ T-cells to proliferate and promote immunologic memory." (PMID 31487807, 2019). "CD4+ T cells were required to protect mice from a lethal dose of ZIKV after infection intravaginally, but not intravenously." (PMID 30677097, 2019). "Taken together, these results indicate that both the VZV Ellen and vaccine strain can infect all immune cell populations in the PBMC pool with preferential infection of monocytes, followed by NK cells, NKT cells and B cells; with CD4+ and CD8+ T cells being the least permissive to infection." (PMID 30870532, 2019). "Among European Union member states, a CD4 back-calculation model, which assigns probable place of HIV infection among migrant populations by estimating the time of infection and comparing it with the time of arrival in the host country, is being promoted to inform prevention programs." (PMID 30892272, 2019). "Male PBMCs had lower CD3+, CD4+, and CD8+ T cells percentages during infection compared to females." (PMID 31477151, 2019). "However, immune activation or langerin inhibition allows infection of LCs, which subsequently transmit HIV-1 to CD4+ T cells." (PMID 31856198, 2019). "The absence of CD4 T cells during the onset or throughout the infection leads to severe CD8 T cell exhaustion, poor humoral immunity, and high levels of viral persistence." (PMID 30781904, 2019). "Among them, the IFN-γ-expressing H99 (H99γ) and a mutant strain lacking SGL1 gene are avirulent in murine infection models and provide full protection against challenge by H99 in both wild-type and also CD4+ T cell-depleted mice." (PMID 31772051, 2019). "Two hours following infection, activated and non-activated CD4+ T cells were assessed for viral entry, as evidenced by β-lactamase-mediated cleavage and fluorescence of the cytoplasmic substrate." (PMID 30943397, 2019). "IRF2, RNASEL and SP100 are all upregulated in the CD4 cells of vervet monkey but not of macaques one day post infection." (PMID 31765391, 2019). "As was the case with RhIVBG505, the highest dose of 3BNC117 gave apparently sterilizing protection against RhIVCH505 infection, with undetectable plasma viremia and no CD4+ cell depletion." (PMID 31644426, 2019). "This protein has been studied in several infections; however, this is the first study to evaluate the plasma concentrations of functional MBL in PLWHA coinfected with HHV-8 and correlate the concentrations with HIV viral load and CD4 counts." (PMID 30606111, 2019). "In this study, we aimed to characterise the development and maintenance of memory CD4+ T cell subsets in adult mice to identify the nature and timing of the signals driving these dynamics in the absence of overt infection." (PMID 31742553, 2019). "While the percentage of CD4+/PD-1+ cells steadily increased in the intestines of VEH/SIV rhesus macaques, their corresponding percentages in THC/SIV rhesus macaques remained stable from 14 until 180 days post-infection." (PMID 31114576, 2019). "All these reflexes should be utilized as neural pathways of physiological reflexes that serve to keep body homeostasis, particularly in the absence of autoreactive CD4+ T cells, which are known to increase with age and/or infection." (PMID 32232103, 2019). "In order for the virus to be completely cleared at the site of infection, an important arm of the adaptive immune response is activated resulting in a cytotoxic T lymphocyte (CD8+; cluster of differentiation) and T helper cell (CD4+) response." (PMID 30787331, 2019). "Fusion of permissive cells with the Jurkat CD4+ T-cell line impaired productive infection as indicated by the absence of GFP+ cells." (PMID 31648236, 2019).
infection (continued). "The main contribution of CD4+ T cells is in the generation and differentiation of CD8+ cytotoxic T cell responses (CTL) required for controlling viral replication, and in the mobilization of CTLs to peripheral sites of infection." (PMID 30921340, 2019). "Since previous results suggested that CD4+ T cell-mediated immunity from the protective effects was not required, we used a model of infection with Galleria mellonella, which lacks T cell-mediated immunity." (PMID 30940711, 2019). "However, activated PBMCs express more physiologically relevant levels of CD4 and HIV-coreceptors than transfected cell lines such as TZM-bl cells, and secrete cytokines upon infection as mucosal tissues." (PMID 31178736, 2019). "In comparison, (d) non-vaccinated mice failed to respond to challenge infection with a potent activation of Th1 CD4+T cell response." (PMID 31293599, 2019). "Given the differential distribution of CD8+ and CD4+ TRM (RAMD and iBALT, respectively), it seems likely that the primary involvement of CD4+ T cell help during CD8+ TRM formation is exerted during the acute phase of infection." (PMID 31024560, 2019). "Laboratory mice develop populations of circulating memory CD4+ T cells in the absence of overt infection." (PMID 31742553, 2019). "The role of B. pseudomallei-specific CD4+ T cells was shown to be important for host resistance, and IFN-γ-mediated immunity has a critical role for survival in humans and in murine models of infection (35, –, 41)." (PMID 30602524, 2019). "Using this system, we assessed viral entry and levels of productive infection, comparing activated to non-activated CD4+ T cells from healthy donors." (PMID 30943397, 2019). "Consistent with a role of mDCs in supporting HIV-1 trans-infection in lymphoid tissues, it was shown that depletion of lymph node-resident mDCs in tissue-suspension cultures reduced the efficiency of HIV-1 infection of CD4+ T cells." (PMID 31244850, 2019). "Here, we demonstrate that both viral mRNAs and antigens are detectable in CD4+ T cells despite the absence of productive infection." (PMID 31648236, 2019). "Further, we analyzed the relationship between the three significantly altered chemokines and CD4+ T-cell count at the 1-year-infection point without antiretroviral therapy, as an approximation of HIV disease progression." (PMID 31836011, 2019). "However, the proportion of both SP CD4+ and SP CD8+ cells expressing Tim‐3 was significantly higher in chronic than in past infection (P < 0.01)." (PMID 30972915, 2019). "In addition, TNF-α is known to upregulate the expression of the transcription factor NF-kB, which is required for HIV proviral transcription in CD4+ T cells, and so likely accelerates the lytic HIV lifecycle and CD4+ T cell depletion during infection." (PMID 31156637, 2019). "To determine whether adoptive transfer of cells to naïve mice enhanced the Th1 and Th17 responses in the lungs after infection, we assessed IFN-γ and IL-17 production by ICS and flow cytometry on lung CD69+CD4+ TRM cells 13 days post challenge." (PMID 30866771, 2019). "Surprisingly, HIV-1 binding to DCIR in DCs, which leads to productive infection also triggers the release of exosomes containing the pro-apoptotic protein DAP-3, which increased spontaneous apoptosis in uninfected CD4+ T cells." (PMID 31708924, 2019). "Efforts to purge the latent HIV reservoir predominantly involve reactivation of viral production from latently infected CD4+ T cells followed by clearance of these cells through a combination of viral and cell-mediated cytotoxicity while ART prevents subsequent rounds of infection." (PMID 31719184, 2019). "Delay of infection correlates with non-neutralizing antibody effector function, Env-specific CD4+ T-cell responses, and gp120 V2 loop specific antibodies." (PMID 30778066, 2019). "However, only the pNL4-3-ΔENV-Nef-P2A-SBP-ΔLNGFR virus expressed high levels of LNGFR 24 hr post-infection in both CEM-T4s and primary human CD4+ T cells." (PMID 30857592, 2019).
infection (continued). "A significant correlation was found in vaccine group A, the only group exhibiting significant resistance against virus challenge, between peak cytokine response and time to infection for CD4 T cells (P = 0.0083, R2 = 0.7132) but not for CD8 T cells." (PMID 31413132, 2019). "During LCMV-Docile infection, the absence of pDCs in mice results in an a defective CD4+ T cells response and consequently a defective CD8+ T cell reaction." (PMID 30791575, 2019). "Together, these data show that HIV-1 Envs derived from brain or immune tissue of patients with or without neuroAIDS were unable to mediate infection of cells expressing CCR5 but not CD4." (PMID 30415390, 2019). "Depletion of CD4+ T-cell prior to infection, did not affect the frequency of flu-specific CD8+ T-cells in the lung parenchyma, but these cells had reduced expression of the Trm markers CD103, CD69, and CXCR3." (PMID 31130965, 2019). "CD4+ T cells in the iliac LNs of intravaginally infected mice showed an identical pattern of expansion of TFH and IL-10-producing CD4+ T cells and reduction in Treg cells on day 10 post-infection." (PMID 30677097, 2019). "This allows us to conclude that the observed differences in infection are due to defects in entry and that our gating strategy did not exclude infected cells because they no longer express CD4." (PMID 31181085, 2019). "The ratio of CD4+/CD8+ and absolute number of CD4+ determine whether the immune system is strong and predict the risks of complications and infections." (PMID 31015850, 2019). "Thirty-two HIV-infected individuals were followed for at least 1 year without antiretroviral therapy, with median CD4+ T-cell count and VL at 1-year-infection of 412 cells/μL and 22,887 copies/mL, respectively." (PMID 31836011, 2019). "Moreover, after infection, the animals pretreated with the VRC01/anti-α4β7 combination had higher CD4 counts compared to the other treatment groups and lower amounts of virus in the gut compared to the control group." (PMID 31083697, 2019). "Notably, CD4+ T cells contributed to the ZIKV-specific plasma cell, germinal center (GC) B cell, and IgG responses after both intravenous and intravaginal infection." (PMID 30677097, 2019). "Secondly, the CD4 T cell fractions in SAT and VAT exhibit similar level of HIV DNA during the chronic phase of the infection – suggesting that the common features of SAT and VAT (rather than the specific properties of each type of AT) favor viral infection and/or persistence." (PMID 31921023, 2019). "Similarly, mice treated with 1.2 mg/kg sublancin showed increased frequencies of CD4+ (P < 0.05) and CD8+ (P = 0.06) T cells 36 hours after infection." (PMID 31583256, 2019). "Such cell-to-cell transfer of virus, termed trans infection, has been extensively described by us and others as a highly efficient mechanism of transfer of HIV-1 to CD4+ T cells by professional antigen-presenting cells (APCs), that is, myeloid DCs and macrophages and B lymphocytes." (PMID 31304185, 2019). "Although, the CD4+ T helper cell response is not known to contribute significantly in the resolution of acute LCMV-Arm infection in WT mice, IFN-Is are involved in their activation and differentiation." (PMID 30791575, 2019). "Spleen cells from CD4+ or CD8+ T cell-depleted mice with or without PyNL infection (day 10 post infection; p.i.)were analyzed by flow cytometry." (PMID 31608052, 2019). "Furthermore, both the number and function of CD4+, CD8+ T cells, and NK cells in patient 35 returned to pre-infection level after one month of anti-infection treatment." (PMID 31857499, 2019). "A fraction of those individuals is also classified as long term nonprogressors (LTNP), as they maintain CD4+ T cell counts > 500 cells/mm3 during more than 10 years of infection without progressing to AIDS in the absence of antiretroviral treatment." (PMID 31277590, 2019).
infection (continued). "Correlates of delayed infection were non-neutralizing Ab effector functions and Env-specific CD4+ T-cell responses." (PMID 31390725, 2019). "To determine whether CECs mediate HIV-1 trans-infection of CD4+ T cells as reported for RBCs, we incubated CECs or RBCs with HIV-1 (exactly similar to the methods used for infecting CD4+ T cells)." (PMID 31772057, 2019). "The CD3+ cells normalized levels at this time point were comparable among the groups, while the CD4+ and CD8+ normalized values were significantly different in C57BL/6 mice compared to both BALB/c and SV/129 strains: the infection induced an increase of CD4+ and a decrease of CD8+ T cells." (PMID 30881923, 2019). "To analyse if CD8+ T cells are actually dispensable for control of the FV challenge after MCMV.env immunization, we performed depletion experiments where CD8+ T cells, or CD4+ T cells as control, were depleted from MCMV.env immunized mice starting one week before FV challenge infection." (PMID 31568492, 2019). "To analyse functional HBV-specific CD4 and CD8 T cells at the site of infection, we stimulated FNA and biopsy extracts with overlapping peptides (OLPs) spanning core and envelope proteins and tested for interferon (IFN)-γ responses by intracellular cytokine staining (ICS)." (PMID 30487267, 2019). "These DCs are capable of capturing HIV-1 and mediate viral transmission to target CD4+ cells via trans-infection, even in a basal state where no apparent activation is detected." (PMID 31861617, 2019). "In Case 1, a B. anthracis-specific CD4+ T-cell response was observed and maintained over time (at least until Day 73 after infection), even in the absence of a measurable antibody response." (PMID 31213220, 2019). "Thus, while epitopes from all DENV proteins can potentially be recognized by CD4+ and CD8+ T cells, the precise pattern of immunodominance depends on the T cell type, the infecting serotype, and the individual's history of infection." (PMID 31244855, 2019). "HCV increases the frequency of gC1qR+CD4+T cells, and viral persistence maintains this frequency at the late phase of infection, while individuals resolving HCV infection do not." (PMID 30909456, 2019). "Moreover, at day 8 post-infection, we observed a significant difference in the number of CD3+CD4+ T cells that infiltrated the cornea of B6 mice infected with the virulent vs. less-virulent strains." (PMID 31367214, 2019). "Using high CD4+ T cell counts as a proxy for recently infected subjects, we observed higher CD4+ T cell counts in recently infected subjects compared to those with established infection by BRAI but not by LAg." (PMID 31125356, 2019). "In non‐human primates, preferential SIV detection in α4β7+ CD4+ T cells was observed in the first 10 days of infection, but not subsequently; these data have not been confirmed in humans." (PMID 31339004, 2019). "IRF-8 expression in all myeloid subsets did not associate with age, CD4 count or nadir, CD8 count, CD4/CD8 ratio, or total self-reported years of infection or on ART (data not shown)." (PMID 31849969, 2019). "Mouse microglia express TLR1-9 and TMEV infection activates these cells to upregulate cytokines, chemokines, MHC class II, and costimulatory molecules, enabling microglia to efficiently present antigens to CD4+ T cells." (PMID 30669615, 2019). "Although we did not test pre-infection CD4+ T-cell counts in these participants, the mean pre-infection value was 800 cells/μL in this cohort; therefore, we set 800 cells/μL as the initial CD4+ T-cell count pre-HIV infection." (PMID 31836011, 2019). "CAF09-adjuvanted WIV did not induce significant numbers of CD4 T cells and accordingly, depletion of CD4 T cells during infection did not affect clinical scores or lung virus titers." (PMID 30984200, 2019). "Yet, ART does not eliminate the infection since replication-competent HIV-1 survives in latently infected CD4+ T cells during many years of ART." (PMID 30716099, 2019).
infection (continued). "Although HPgV-1 infection is persistent, our data suggest that the time of infection does not influence HIV-1 VL or CD4+ T-cell counts in coinfected subjects." (PMID 31309117, 2019). "The immune response during the early stages of infection is resilient and not readily disrupted by use of immunosuppressive agents like dexamethasone or depletion of CD4 T cells at the time exposure." (PMID 31921129, 2019). "In splenocytes stimulated either with H. meleagridis antigen or PMA/ionomycin, IFN-γ-producing CD4+ T cells from infected chickens increased in comparison to cells from non-infected birds 2 weeks and 5 weeks post-infection." (PMID 31806018, 2019). "Infection of A1Ifnar-/- mice with reduced doses of RhIVBG505, RhIVDu156, RhIVSF162, or RhIVCH505 revealed that 103 PFU established robust infection with profound CD4+ T-cell depletion, albeit with reduced peak plasma viremia (105–107 RNA copies/ml)." (PMID 31644426, 2019). "Thus, more research is needed to investigate HIV persistence in naïve CD4+CD25+CD127lowCD45RO− Tregs (nTregs) and their memory counterparts, CD4+CD25+CD127lowCD45RO+ Tregs (mTregs) during the course of the infection." (PMID 31681335, 2019). "Thus, to better characterize the infection status of bystander CEM cells in our system, we evaluated levels of intracellular p24 and cell surface CD4 in both HSA+ and HSA− CEM cells 4 days postinfection." (PMID 31848282, 2019). "We then measured the reporter activity upon infection of the HeLa-CD4 LTR-Luc cells with the three viruses, with or without 100 nM dCA." (PMID 31266880, 2019). "Frequencies of Foxp3+ Treg within the CD4+ T cell population were similar in the small intestine of both mouse lines and did not change during infection in BALB/c and C57BL/6 mice." (PMID 31889073, 2019). "For instance, as the Swiss 4.5K screen recruited individuals at different stages of the infection, whereas the Amsterdam IDU cohort was selected from a narrower range, the predictive capacity of CD4 and viral load may differ." (PMID 31027215, 2019). "The capture and spread of HIV-1 to FDCs is of importance because while FDCs are not permissive to infection, they can carry infectious virions and transfer them to bystander CD4+ T cells." (PMID 30669528, 2019). "The production of these chemokines leads to an influx of CCR5+ CD4+ T cells to sites of infection and fuels the expansion of infected founder CD4+ populations during acute vaginal SIV infection, thereby allowing foothold infection to be established." (PMID 31156637, 2019). "We determined that SEA, through kappa-5, can potently block DC-SIGN mediated HIV-1 trans-infection of CD4+ T-lymphocytes, but not block cis-infection." (PMID 31487324, 2019). "C3HeB/FeJ mice infected with MAC was associated with increased numbers of CD3+CD4+CD44hi and CD3+CD8+CD44hi activated T effector cells and CD3+CD4+CD44hiCD127+ and CD3+CD8+CD44hiCD127+ memory T cells between 40 and 50 days after infection, followed by diminished numbers." (PMID 31001241, 2019). "Neutralization breadth correlates with viral load and CD4+ T cell decline, which partly explains why bnAbs have no impact on disease progression in natural infection." (PMID 31390725, 2019). "We observed the dynamics of CD4+ and CD8+ percentage in a period of 72 h after infection." (PMID 31014302, 2019). "The infected CD4+ T cells were found mainly in lymph node samples, but there was no apparent change in pattern over the course of infection, indicating that there was little change in cell subtypes constituting the infected CD4+ T cell population." (PMID 30782653, 2019). "Indeed we have already reported that CD69+CD4+ TRM cells accumulate in the lungs during infection with B. pertussis, expand after re-infection and promote clearance of the secondary infection." (PMID 30866771, 2019). "The frequency of cytokine-producing CD8+ T cells was lower (<5%) than that of CD4+ T cells (20% to 40%) and did not change much over the course of infection." (PMID 30642899, 2019).